CD4 (CD4 molecule)
Diseases named in the same sentence as CD4 in open-access papers (continued):
Sharing a sentence is not in itself a finding about the gene and the disease.
influenza (continued). "CD4+ T cell and CD8+ T cell cross-reactive memory responses have also been shown to affect influenza infection susceptibility and severity." (PMID 29898768, 2018). "In this review, we will discuss the consequences of aging on CD4+ T cell differentiation and function and how this influences the initial CD4+ T cell effector responses to influenza infection." (PMID 29616390, 2018). "In the infection model studied here, we also observed a strong enrichment for IFN-γ-producing cells in the lung, for all epitopes examined, a result consistent with the Th1 CD4 T cell phenotype typical of influenza CD4 T cell immunity." (PMID 29681900, 2018). "Accordingly, we believe the CTA1-3M2e-DD, generating both lung resident memory CD4+T cells and M2e-specific antibodies, is a good candidate for a broadly protective influenza vaccine." (PMID 30271406, 2018). "Influenza-infected mice given anti-CD4 or isotype antibodies also had a similar frequency and total number of lung MCp, suggesting that lung CD4+ T cells are dispensable for influenza-induced recruitment of MCp to the lung." (PMID 30337928, 2018). "Infection was not required at this stage, since antigen-pulsed APC were sufficient to support optimal memory CD4 T cell generation and maintenance that was able to protect a naïve host from an otherwise lethal influenza challenge." (PMID 29632538, 2018). "Intranasal administration of Live Attenuated Influenza Vaccine (FluMist) in a mouse model induced both CD4+ and CD8+ TRM that provided a degree of cross-strain protection independent of TCM and antibodies." (PMID 30038624, 2018). "The generation of functional TRM that protect against heterosubtypic influenza infection appear to be dependent on signals from CD4+ T cells." (PMID 30038624, 2018). "Influenza-infected mice given anti-CD4 antibodies had a similar yield of lung MNC as influenza-infected mice given isotype control antibodies." (PMID 30337928, 2018). "Since CD4+ T cells are necessary for robust humoral and cell-mediated flu responses, research investigating the rate and magnitude of these age-related changes throughout the course of infection is of great significance." (PMID 29616390, 2018). "The CD4+ T cell field is less developed than the CD8+ T cell field for influenza research, due to the availability of MHCI tetramers and transgenic mouse strains." (PMID 29587436, 2018). "Our studies revealed that when assayed by epitope-specific cytokine production, the epitope specificity of influenza-specific CD4 T cells is very broad in the dLN and that this diverse peptide specificity persists in cells that home to the lung." (PMID 29681900, 2018). "This leaves the majority of human research regarding CD4+ T cell changes during flu infection focusing on peripheral blood CD4+ T cells during flu recovery or using vaccination responses as predictive markers for infection responses." (PMID 29616390, 2018). "In an ex vivo restimulation assay, spleen cells were cocultured with influenza-loaded bone marrow-derived dendritic cells (BMDCs) to study the effects of 2′FL on vaccine-specific CD4+ and CD8+ T-cell proliferation and cytokine secretions." (PMID 29593719, 2018). "It is now clear that influenza-specific CD4 T cells have many diverse functions in the lung, some of which, such as cytotoxicity and cytokine production, likely involve contact with APC [reviewed in Ref." (PMID 29681900, 2018). "We detected influenza-specific CD4+ T-cell responses following vaccination with the licensed trivalent influenza vaccine and found that these correlated with antibody measurements." (PMID 30573748, 2018). "Comparing CD38 expression in influenza specific CD4+/CD45RO+ memory T cells in pre and 14 days post influenza vaccination samples, we observed that CD38 expression was only present in the post vaccination samples." (PMID 30619245, 2018).
influenza (continued). "Because of the importance of this issue, in this study, we sought to empirically examine the CD4 T cell peptide specificity, drawn from the endogenous, polyclonal CD4 T cell repertoire that homes to the lung after influenza infection." (PMID 29681900, 2018). "In the few rare studies where such data are available, the number of influenza-specific CD4+ and CD8+ T cells, as well as the magnitude of cytokine response, are far greater in the lungs compared to the blood." (PMID 29587436, 2018). "It has also been shown that pTFH cells isolated post-influenza vaccination are better able than other CD4+ T-cell subsets to support B-cell differentiation and to stimulate influenza-specific antibody secretion." (PMID 28769922, 2017). "Many CD4+ T-cells responding to influenza in the lung produce IL-10, largely in cells also producing IFN-γ." (PMID 28769922, 2017). "Women who subsequently started ART should have proliferation of influenza-specific CD4+ memory T cells after vaccination, some of which would be latently infected with HIV-1." (PMID 28193244, 2017). "A CD4 T cell clone recognizing this epitope exhibits cytotoxicity to a variety of influenza strains, including avian H5N1 virus." (PMID 28167943, 2017). "Following primary influenza infection, a CD4 T cell response of broad specificity develops that includes reactivity to epitopes within all of the major viral proteins." (PMID 28493882, 2017). "Heterosubtypic immunity is mainly mediated by cross-reactive cytotoxic CD8+ T cells, and pre-existing influenza-specific CD4+ and CD8+ T cells effectively cross-reacted to the newly emerged influenza A(H1N1)pdm09 virus." (PMID 29145441, 2017). "Hemagglutination inhibition assays were performed to quantify neutralizing antibodies; functional influenza-reactive CD4 T cells were quantified by flow cytometry, and influenza-specific CD8 T cells were enumerated with MHC Class I tetramers." (PMID 28723925, 2017). "During influenza infection, the binding of T-bet to cytotoxic gene promoters in CD4 T cells is regulated by Blimp-1 expression via a mechanism involving IL-2, type I interferons, and STAT2 signaling." (PMID 28167943, 2017). "We observed modest, but significantly-increased fractions of influenza-reactive cells among total CD4 T cells at 9–15 days after vaccination, compared to pre-vaccination." (PMID 28723925, 2017). "The study found enrichment of interferon, cell cycle genes, apoptosis, DNA damage, B cell, CD4+ T helper cells, and neutrophils in influenza-induced versus bacterial pneumonia (i.e., upregulation in viral samples)." (PMID 29070035, 2017). "The influenza antigen-specific immunity was impaired, as represented by the attenuated HA-specific CD4+ T cell responses." (PMID 28646236, 2017). "While age and recent seasonal influenza vaccination tended to reduce HI antibody, memory B-cell, and, to a lesser extent, CD4+ T-cell responses, these effects appeared to be partially or completely compensated for by the use of AS03." (PMID 28446441, 2017). "Naïve influenza HA (Hemagglutinin) antigen-specific CD4+ T cells were adoptively transferred on the same day of infection." (PMID 28646236, 2017). "Taken together, the data show that CD30 is dispensable for both CD8 and CD4 T-cell expansion during acute influenza infection." (PMID 28993768, 2017). "For the analysis of local effects of the influenza and hepatitis B vaccines on Treg, we vaccinated mice and analyzed the CD4+ CD25+ Foxp3+ Treg frequency and phenotype in draining lymph nodes and spleen at several days post vaccination." (PMID 28658271, 2017). "Compared to vaccination with inactivated influenza alone, the addition of CpG induced significantly higher GzmB expression in lung CD4 T cells, which persisted after challenge with lethal PR8 infection." (PMID 28167943, 2017).
influenza (continued). "In this study, the same model of sequential influenza infection was used to determine the effect of selectively priming CD4 T cell memory against epitopes within the HA protein prior to a heterosubtypic viral challenge." (PMID 28493882, 2017). "CD4+ T-cells in the lung expressing GrB and perforin have cytolytic activity against influenza in mice." (PMID 28769922, 2017). "Influenza infection induces HA-specific CD4+ T-helper cells, resulting in a diverse antibody response." (PMID 28769922, 2017). "Type I interferons such as IFN-α signal through STAT2; STAT2-deficient mice exhibit significantly reduced GzmB expression in lung CD4 T cells following influenza infection, supporting the role of this pathway in generating CD4 CTL in vivo." (PMID 28167943, 2017). "Further characterization of baseline CD4 responses confirmed the ability of influenza-specific cells to perform perforin/granzyme-mediate killing of B cell targets." (PMID 28167943, 2017). "Treatment of older subjects with RAD001 prior to influenza vaccination was demonstrated to decrease the percentage of PD-1-positive CD4 and CD8 T cells compared to placebo and enhance the response to influenza vaccination." (PMID 28798751, 2017). "Mouse models support this idea, as aged mice exhibited delayed, but higher magnitude, CD4 CTL activity during influenza infection compared to younger mice." (PMID 28167943, 2017). "This IL-10 production by influenza-specific CD4+ T-cells results in reduced protection by suppressing cytokine production in Th17 cells, but also plays an important role in limiting immunopathology." (PMID 28769922, 2017). "As previously discussed, multiple groups have shown that CD4 CTL are generated following acute influenza infection [recently reviewed in Ref." (PMID 28167943, 2017). "During acute influenza infection, protective CD4 effectors appear to be specifically generated at the site of infection in the lung, where inflammatory signals and antigen are highly concentrated." (PMID 28167943, 2017). "CD4+ T cell responses have been shown to be important for influenza protection in mouse models and in human volunteers." (PMID 28421076, 2017). "To determine the roles of T cells in inducing IgG isotype-switched antibodies and protective immunity after influenza vaccination, we immunized CD4 KO and CD8 KO mice." (PMID 29276514, 2017). "Such selective arming of the CD4 T cell compartment thus has the potential to decrease infection rates, morbidity, and mortality on the emergence of the next influenza pandemic." (PMID 28493882, 2017). "The influence of influenza immunization on CD4+ T cells in HIV-infected patients thus remains controversial." (PMID 28694558, 2017). "In summary, through the combination of influenza reverse genetics, in vivo infection, multi-parameter flow cytometry and antigen-specific CD4 T cells, we have been able to identify many cell types within the respiratory tract that access influenza antigens." (PMID 28883436, 2017). "For example, the receptor for epithelial cadherin CD103 appears highly expressed only in CD4+ CTL generated in the lungs of influenza-infected mice." (PMID 28289418, 2017). "Improved immune responses were, however, detected against at least one strain in the trivalent influenza vaccine in women with CD4+ T-lymphocyte counts of >350 cells/μL." (PMID 28883971, 2017). "Of these antigens, three were found to elicited interferon (IFN)-γ-producing CD4 cells in the majority of human test subjects: inactivated cytomegalo-, parainfluenza-, and influenza virions (CPI)." (PMID 29215584, 2017). "The role of CD4+ T cells in supporting antibody responses against influenza HA has been accepted for many years." (PMID 29326687, 2017). "Our studies revealed that after infection, both CD45-negative and positive cells from the lung display sufficient peptide:class II complexes to be recognized and elicit cytokine from a polyclonal population of influenza-specific CD4 T cells." (PMID 28883436, 2017).
influenza (continued). "To begin to investigate the impact of aging on CD4 T cells during influenza infection, we examined the distribution of Th subsets in unvaccinated young and aged mice using a scheme developed in the Kaech laboratory." (PMID 27177221, 2016). "Blocking OX40 engagement has been shown to prevent immune‐mediated lung damage in a sublethal influenza infection model by eliminating the influenza‐induced CD4+ and CD8+ T‐cell infiltration within the lung." (PMID 26976612, 2016). "Peripheral TFH subsets in whole blood or fresh human PBMCs of healthy participants have been identified by ex vivo staining following vaccination against influenza, describing memory CD4+CXCR5+ TH cells as the most abundant population." (PMID 27336786, 2016). "CD4+ T cells can also produce all three cytokines after IAV infection, and among influenza-specific CD4+ T cells in human blood, triple cytokine producers are functionally superior to single-producers." (PMID 26910342, 2016). "The challenge for provision of CD4 T cell help for antibody responses to novel strains of influenza is much more profound for avian strains than the pH1N1 2009 strain." (PMID 26834750, 2016). "Specifically, we now had a convenient tool to comprehensively analyse how the CD4 T-cell response to influenza vaccination is shaped by RA and its treatments." (PMID 27571776, 2016). "Collectively, these studies have revealed that CD4 T cells contribute in diverse ways and at different sites in vivo to protective immunity to influenza." (PMID 26834750, 2016). "Much progress by many groups has contributed thus far to our understanding of CD4 T cell function in influenza immunity." (PMID 26834750, 2016). "Our laboratory has used cytokine Elispots and large peptide libraries to assess the viral protein specificity of influenza-specific CD4 T cells in an unbiased approach." (PMID 26834750, 2016). "In another study in influenza infection, Treg cell decreased the availability of IL-2 to naive CD4+ T cells and thereby promoted Tfh differentiation and enhanced GC formation and antibody response." (PMID 27933060, 2016). "In the lungs during influenza infection we also find a significant skewing of the total CD4 population towards Th1 in the young and towards Tfh in the aged at all time points examined." (PMID 27177221, 2016). "Here the authors develop an MHC class II combinatorial technique and apply it to immunophenotype human CD4+ T cells of multiple specificities in response to influenza vaccine in single blood samples." (PMID 27571776, 2016). "Cross-protection can be achieved by activating CD8+ and CD4+ T cells against highly conserved regions of the influenza genome." (PMID 27402904, 2016). "To determine if more aged NP-specific CD4+ T cells exhibited regulatory T cell properties, we evaluated Foxp3 expression in young and aged influenza infected mice." (PMID 27109638, 2016). "Live influenza infections generate large and diverse CD4 effector T cell responses that yield highly protective, long-lasting CD4 T cell memory that can target conserved viral epitopes." (PMID 27148257, 2016). "Animal models have revealed the discrete functions that CD4 T cells play in developing immune response and to influenza immunity." (PMID 26834750, 2016). "As influenza-specific CD4 T cells often have a dominated T helper 1 phenotype, IFN-γ is a prominent effector cytokine produced in response to infection." (PMID 26834750, 2016). "In our view, several key questions need to be resolved in order to better understand the impact of CD4 T cells on human immunity to influenza infection." (PMID 26834750, 2016). "In the host that has not previously encountered a new and potentially pandemic strain of influenza, these HA-specific CD4 T cells must be drawn from the memory pool elicited previously by seasonal strains." (PMID 26834750, 2016).
influenza (continued). "These circulating influenza-reactive CD4 T cells are heterogeneous with regard to expression of chemokine receptors and the gene expression profiles linked to distinct effector functions." (PMID 26834750, 2016). "Investigators have also shown direct effects of memory CD4 T cells in protection against influenza infection." (PMID 27014272, 2016). "While the effect of aging on CD8 T cell responses to influenza has been extensively studied, the impact on CD4 T cells is less well understood." (PMID 27177221, 2016). "As expected (and in line with chemokine receptor expression) influenza-specific CD4+ T cells expressed mainly IFN-γ, along with very low but detectable levels of IL-4 and IL-17." (PMID 27571776, 2016). "A similar concept can operate in influenza infection, with pre-existing CD4+ T cell responses to core viral epitopes shown to enhance antibody responses to envelope glycoproteins." (PMID 27861512, 2016). "During influenza infection, many subsets of CD4 and CD8 effectors are generated that contribute to influenza virus clearance." (PMID 26941738, 2016). "Specifically, during influenza CCR9+ CD4+ T cells are recruited from the lung to intestinal tissues." (PMID 27148490, 2016). "Last, we investigate the influence of biologic treatments on the ability to mount effective CD4+ T-cell responses by examining influenza-specific T cells in rheumatoid arthritis (RA) patients before and after vaccination." (PMID 27571776, 2016). "We had therefore measured activated CD4+ CD40L+ T cell counts after stimulation with the 3 influenza strains in the vaccine." (PMID 26954292, 2016). "For example, with liposome vaccines as novel universal, broadly protective, influenza vaccines against also heterosubtypic virus strains, it will be important to also assess and evaluate CD4+ T cell immunity as a correlate of protection." (PMID 28127567, 2016). "CD4 T cells specific for influenza viral proteins can be readily detected in the circulation of most human subjects, when assayed through approaches, such as HLA-class II tetramer staining, intracellular cytokine staining, and cytokine Elispots." (PMID 26834750, 2016). "Pre-existing memory CD4+ T cells, capable of killing virus-infected cells responded to influenza internal proteins and inversely correlated with less virus shedding and lower disease scores." (PMID 26973644, 2016). "Influenza A virus infection predominantly induces a Th1 response, with most CD4 effectors producing IFNγ though the importance of IFNγ in combating the flu has been debated." (PMID 27148257, 2016). "Recently, it was identified that in influenza the best correlate of protection in a study with healthy human volunteers was the preexisting influenza-specific CD4+T cells." (PMID 28127567, 2016). "Following vaccination all subjects showed an increase in the frequency of influenza-specific CD4 and CD8 T cells on both day 7 and 30 post vaccination." (PMID 26859566, 2016). "In order to understand what is happening in our aging model, we went on to examine the CD4 T cells of influenza-infected mice and interrogate the impact of age on Th subset differentiation." (PMID 27177221, 2016). "Vaccination also stimulates influenza-specific CD4 and CD8 T-cell memory cells that generate effectors that are recruited to the lungs to clear virus-infected cells in the lungs, thus, providing “clinical protection” against disease." (PMID 26941738, 2016). "We suggest strategies for improved influenza vaccines based on our new understanding of the mechanisms by which CD4 memory and functionally specialized effectors are generated." (PMID 27148257, 2016). "While studies have demonstrated that antigen recognition in the lung along with TGFβ signals are required for the formation of CD8 TRM during influenza infection, it is unclear if CD4 TRM cells have similar requirements." (PMID 27148257, 2016).